ABCC1 (ATP binding cassette subfamily C member 1 (ABCC1 blood group))
Diseases named in the same sentence as ABCC1 in open-access papers (continued):
Sharing a sentence is not in itself a finding about the gene and the disease.
breast carcinoma (continued). "This study aimed to explore tagged haplotype covering nucleotide binding domain 1 of ABCC1 in relation with corresponding transcript levels in tissues and clinical phenotype of breast cancer patients." (PMID 25078270, 2014). "The present study addressed yet unexplored associations between genetic variability in NBD1 and adjacent sequences of ABCC1 and clinical course of breast cancer." (PMID 25078270, 2014). "Twelve SNPs selected with the help of HaploView v4.2 pairwise tagging algorithm of the region including NBD1 and surrounding sequences of ABCC1 were genotyped in 540 breast carcinoma patients." (PMID 25078270, 2014). "Recently, it has been reported that ABCC1 is a predictive marker of the highly aggressive subtypes of breast carcinoma." (PMID 25268163, 2014). "In particular, this miRNA was downregulated in a panel of advanced breast cancer tissues and reversely associated with expression levels of Multidrug resistance associated protein (MRP-1/ABCC1)." (PMID 23155457, 2012). "Our comprehensive survey of ABC transporter family gene expression identified ABCC1 as an efflux pump that may have particular relevance in mediating T-DXd resistance in breast cancer, offering a strong rationale for its therapeutic targeting." (PMID 41422323, 2025). "The involvement of ABCC1 in drug resistance has been documented in various cancers, including acute myeloblastic and lymphoblastic leukemia, prostate cancer, non-small-cell lung cancer, neuroblastoma, and breast carcinoma." (PMID 38397468, 2024). "Circ-ABCC1 is upregulated in radio-resistant breast cancer and could induce radioresistance through acting as a decoy of miR-627-5p to increase the level of ABCC1." (PMID 38186573, 2023). "Downregulation of miR-134 may also increase breast cancer doxorubicin resistance by controlling the ATP binding cassette C1 (ABCC1) gene." (PMID 36980610, 2023). "Importantly, both ABCG2 and ABCC1 were described as MDR mediators in breast cancer at THE clinical level." (PMID 36430819, 2022). "Besides ABCG2, ABCC1 is also frequently overexpressed in breast cancer tissues showing correlation with aggressive phenotype and chemotherapeutic resistance." (PMID 36430819, 2022). "Similarly, Low and Shabir discovered that ABCC1 was correlated to breast cancer proliferation in siRNA knockdown cell models." (PMID 33801148, 2021). "Besides MYCN oncogene regulates the transcription of ABCC1, the transfection of MCF-7/VP-16 breast cancer cells with miR-326 can downregulate ABCC1 expression and increase cancer cell sensitivity to etoposide and doxorubicin." (PMID 33953682, 2021). "Interestingly, S1P, which can be exported by ABCC1, is able to mediate proliferation and migration of breast cancer cells." (PMID 32718079, 2020). "Furthermore, it has been demonstrated that ABCC1 is a direct c-MYC target in breast cancer and glioblastoma cells." (PMID 32718079, 2020). "Previous studies have shown that ABCC1 expression is a negative prognostic marker, associated with a decreased survival rate in breast cancer patients and an increased risk of relapse." (PMID 33081264, 2020). "Similarly, ABCC1 overexpression was correlated to increased drug resistance and stemness, while the knockdown of ABCC1 reversed these effects in breast cancer cells." (PMID 32883003, 2020). "Importantly, a direct correlation between c-MYC overexpression and ABCC1 upregulation has been observed in breast cancer and aberrant expression of c-MYC has been detected in a number of human malignancies including prostate epithelial neoplasia." (PMID 32718079, 2020). "In this study, the aim was to investigate whether ABCC1 or ABCC4 play a role in the proliferation or migration of breast cancer cell lines MCF-7 (luminal-type, receptor-positive) and MDA-MB-231 (basal-type, triple-negative)." (PMID 33081264, 2020). "For instance, ABCC1 and ABCG2 have been associated with chemoresistance in breast cancer." (PMID 28912626, 2017).
breast carcinoma (continued). "Also, our data showed that knockdown of ABCC3, significantly increased the retention of doxorubicin in breast cancer cell lines, better than that achieved by ABCC1 knockdown." (PMID 27171227, 2016). "Thus, our these data revealed that similar to inhibition of ABCC1 with MK-571, knockdown of ABCC1 in breast cancer cells also promoted their increased retention of doxorubicin, consistent with a previous report on Jurkat cells." (PMID 27171227, 2016). "Since we observed that breast cancer samples derived from patients treated with 5-flurouracil and cyclophosphamide showed upregulation of ABCC1 and ABCC3, we further went ahead to check the expression of ABCC1 and ABCC3 upon 5-fluorouracil (3 μM) treatment in breast cancer cell lines." (PMID 27171227, 2016). "In contrast, high expression levels of ABCC1 indicates poor prognosis for breast carcinoma." (PMID 26287967, 2015). "Taken together, our study shows that genetic variability in the nucleotide binding domain 1 has a significant impact on the ABCC1 transcript level in the target tissue and may modify survival of breast cancer patients." (PMID 25078270, 2014). "Previous reports have shown that ABCC1 is a negative biomarker associated with a decreased survival rate and an increased risk of relapse in colorectal cancer, lung cancer, and breast cancer." (PMID 34386492, 2021). "This might suggest that ABCC1 plays a role in the proliferation of breast cancer cells." (PMID 33081264, 2020). "Therefore, in this study, we investigated whether ABCC1 or ABCC4 are involved in cellular proliferation or migration in breast cancer cell lines." (PMID 33081264, 2020). "Amazingly, a single miRNA could affect numerous of target genes coincidently, for instance, it has been reported that miR-134 suppresses progression of melanoma by down-regulating CD86; and miR-134 could modulate resistance to doxorubicin in human breast cancer cells by repressing ABCC1 oncogene." (PMID 27166267, 2016). "Thus, knockdown of ABCC1 rendered breast cancer cells chemo-sensitive." (PMID 27171227, 2016). "Thus, our data revealed that increase in the expression of ABCC1 on chemotherapy treatment reduces the retention of doxorubicin in breast cancer cells and this could be rescued by MK-571." (PMID 27171227, 2016). "In addition, we observed that treatment of breast cancer cell lines in vitro with anti-cancer drugs routinely used in the clinic to treat breast cancers (doxorubicin, mitoxantrone and 5-flurouracil) also increased the expression of ABCC1 and ABCC3 in these cells." (PMID 27171227, 2016). "ABCB1, the first identified ABC transporter, is well-known for its role in drug resistance, and subsequent discoveries revealed ABCC1 and ABCG2 as contributors to multidrug resistance in lung and breast cancer cells, respectively." (PMID 38397468, 2024). "The study showed that, like the ABCC1 gene, the ABCC3 gene was overexpressed in stage III primary breast cancer." (PMID 36674773, 2023). "To further clarify the relationship between TM expression level and curcumin resistance, we investigated the gene expression level of several drug-resistant genes such as LRP1, MDR1, ABCC1, and MRP5 after curcumin treatment in ER+ breast cancer cells." (PMID 37239055, 2023). "They observed that the expression level of the ABCC1 and ABCC3 genes is elevated in breast cancer tissue, especially after treatment with anticancer drugs." (PMID 36674773, 2023). "In contrast, long (12-days) exposure to talazoparib has been found to upregulate ABCB1, ABCC1, and ABCG2 mRNAs in another breast cancer model, MCF-10A." (PMID 36430819, 2022). "High expression of ABCC1 and low expression of ABCC8 are correlated with the aggressiveness of breast cancer." (PMID 34650973, 2021).
breast carcinoma (continued). "On the mRNA level, the efflux transporters ABCB1, ABCC1, and ABCG2 were found expressed in human heart, in normal and tumorous breast tissue, and in human breast cancer cell lines MCF-7, MDA-MB-231, and ZR-75-1." (PMID 35008681, 2021). "First, we evaluated the ALDH activity, the expression of BCSC genes (Nanog, Sox2 and Oct4), multiresistance pumps (ABCG2, ABCC1 and ABCB1) and the BCSC frequency (CD44+CD24+CD49+EPCAM+) in three human breast cancer cell lines." (PMID 33184339, 2020). "MK571, which inhibits both ABCC1 and ABCC4, and Reversan, which inhibits ABCC1, were the only inhibitors to affect the proliferation of the breast cancer cells." (PMID 33081264, 2020). "LncRNAs have been found to regulate the expression of ABCB1, ABCC1 and ABCG2 and modulate therapy responses in breast cancer, lung cancer and gastric cancer." (PMID 32872162, 2020). "Promoter methylation of ABCB1, ABCC1, and ABCG2 has been investigated in tumor, tumor-adjacent, and tumor-distant tissues from 16 breast cancer patients and normal breast tissues from four healthy women." (PMID 33066132, 2020). "Using both small molecule inhibitors and siRNA knockdown of ABCC1 and ABCC4, we investigated the impact of these transporters on the proliferation, clonogenic capacity, migration, and invasion of the breast cancer cell lines." (PMID 33081264, 2020). "In breast cancer and glioblastoma cell lines, the downregulation of MYC protein resulted in suppression of ABCC1, being a putative mechanism to sensitize tumors to chemotherapy." (PMID 31192117, 2019). "This was accompanied by an increase in breast cancer stemness (SOX2, OCT4, and NANOG levels) and significant increase in the levels of key drug transporters (ABCG2, ABCB1, and ABCC1)." (PMID 31867270, 2019). "ABCB1, ABCB5, ABCB8, ABCC1, ABCC2, ABCC3, and ABCG2 were considered to confer resistance to doxorubicin on the breast cancer cells." (PMID 30202239, 2018). "The roles of ATP-binding cassette transporters, such as ABCC1, ABCC11, and ABCG2, in breast cancer patients have been reported." (PMID 28912626, 2017). "Further, ABCC1 and ABCG2 are highly expressed in core basal subtype, which is one of the most aggressive breast cancer subtypes, while ABCC11 is highly expressed in the HER2 or core basal subtypes." (PMID 28912626, 2017). "In the present study, we determined the promoter methylation patterns of ABCB1, ABCC1 and ABCG2 in human cancer cell lines, MDR cell models and tumor, tumor-adjacent and tumor-distant tissues from breast cancer patients." (PMID 27689338, 2016). "We observed that similar to ABCC1, the transcripts levels of ABCC3 was significantly high in breast cancers compared to adjacent normal tissue." (PMID 27171227, 2016). "To do so we over expressed ABCC1 and ABCC3 genes by transient transfection of pCMV-ABCC1 and pCMV-ABCC3 constructs into MDA-MB-231 and BT-474 breast cancer cell lines." (PMID 27171227, 2016). "While our data on ABCC1 are consistent with previous studies, we now additionally report the increased expression of ABCC3 on chemotherapy treatment in breast cancer cells." (PMID 27171227, 2016). "We observed that similar to ABCC1, the expression of ABCC3 is elevated in breast cancers, particularly following chemotherapeutic drug treatment." (PMID 27171227, 2016). "Other reports showed that ABCC1, ABCC11 and ABCG2 are highly over-expressed in subtypes of aggressive breast cancer and that increased expressions of ABCC1 and ABCC11 were significantly associated with shorter disease-free survival." (PMID 26883574, 2016).
breast carcinoma (continued). "Taken together our results demonstrated that similar to ABCC1, overexpression of ABCC3 also reduces the retention of anti-cancer drugs in breast cancer cells." (PMID 27171227, 2016). "Next we investigated the effects of chemotherapeutic drug treatment on the expression of ABCC1 and ABCC3 in established breast cancer cell lines." (PMID 27171227, 2016). "Our data is consistent with previous reports on overexpression of ABCC1 in breast cancers, while additionally identifying ABCC3 overexpression in high grade breast cancers." (PMID 27171227, 2016). "Here we pre-treated breast cancer cell lines (MDA-MB-231 and BT-474) with 20 μM of MK-571, a specific ABCC1 inhibitor, for 1 hour, followed by treatment with 0.5 μM rhodamine 123, a standard substrate for retention studies." (PMID 27171227, 2016). "In this study we show that ABCC1 and ABCC3 were significantly overexpressed in a large number of breast cancer samples compared to normal." (PMID 27171227, 2016). "Further, similar to knockdown of ABCC1, knockdown of ABCC3 also significantly increased the retention of chemotherapeutic drugs in breast cancer cells and rendered them more chemo-sensitive." (PMID 27171227, 2016). "We next performed doxorubicin retention assay upon ABCC1 inhibition to check the retention of doxorubicin in various breast cancer cell lines (MDA-MB-231, BT-474, MCF-7 and HCC-1806) as well as in primary breast cancer tissue samples." (PMID 27171227, 2016). "Consistent with this we observed that the expressions of ABCC1 and ABCC3 in chemotherapy-treated breast cancer derived tissue samples were significantly upregulated compared to chemo-naive breast cancer derived tissue samples." (PMID 27171227, 2016). "Our three bisulfite PSQ methods were applied to determine the promoter methylation levels of ABCB1, ABCC1 and ABCG2 in biopsy samples from 16 breast cancer patients." (PMID 27689338, 2016). "We further compared the effect of ABCC1 and ABCC3 knockdown on CD44high/24low marker profile that identifies breast cancer stem cells." (PMID 27171227, 2016). "Together, our data revealed that treatment with chemotherapeutic drugs enhances the expression of ABCC1 and ABCC3 in breast cancer cells both in vivo and in vitro." (PMID 27171227, 2016). "In this study we investigated the expression of ABCC1 and ABCC3 in breast cancers and assessed their role in cancer drug resistance and stemness." (PMID 27171227, 2016). "In breast cancer, miR-451 and miR-326 increase the chemosensitivity of cells to doxorubicin via direct targeting of ABCB1 and ABCC1, respectively." (PMID 25860815, 2015). "All analyzed breast cancer cells depicted similar expression levels of PANX1 and ABCC1 whereas a considerable variability of ANKH and SLC22A11 expression was observed." (PMID 25496233, 2014). "To further confirm the functional role of NRF2 in regulating ABC transporter expression, we next conducted chromatin immunoprecipitation analysis of NRF2, akin to studies reported for ABCC1 and ABCG2 in human lymphoid cells, breast cancer, lung cancer and prostate cancer cells." (PMID 41372143, 2025). "In breast cancer cells, trans-chalcone and licochalcone A decreased ABCC1 expression in MCF-7 cells and downregulated ABCG2 (but not ABCC1) in BT-20 cells." (PMID 40362377, 2025). "For instance, ABCB1 expression has been linked with increased metastasis in prostate cancer, uveal melanoma, and breast cancer patient cohorts, while the expressions of ABCB5 and of ABCC1 were up-regulated in metastases of patients and patients with melanoma, respectively." (PMID 37851804, 2023). "In our qRT-PCR experiments, talazoparib did not cause significant transcriptional changes in ABCB1, ABCC1, and ABCG2 genes in the MCF-7 breast cancer cells." (PMID 36430819, 2022). "Thus, in the final experimental set, we monitored the effect of talazoparib on the expressions of ABCB1, ABCC1, and ABCG2 in breast cancer MCF-7 cells." (PMID 36430819, 2022).
breast carcinoma (continued). "Consequently, inhibiting ABCC1 or ABCG2 with pharmacological inhibitors decreases estradiol-mediated release of S1P and dihydro-S1P and ERK1/2 activation in breast cancer." (PMID 35565311, 2022). "Both ABCC1 and ABCG2 were reported to mediate estradiol-induced S1P release in breast cancer cells." (PMID 35565311, 2022). "In prostate (PC-3, DU145 and LNCaP) and ovarian (OVCAR3 and A2780) cancer cell lines, an autocrine loop that involves GPR55, LPI and the ABC transporter ABCC1 has been demonstrated, whilst GPR55 expression enhances the invasion and migration of human breast cancer cells." (PMID 34324032, 2021). "The knockdown of ABCC1 and ABCC3 reduced the expression of stemness genes (e.g., Nanog and Bmi1) in TNBC cell lines, and the knockdown of ABCC3, but not ABCC1, also reduced the CD44high/CD24low breast cancer stem-like subpopulation." (PMID 33801148, 2021). "In addition, treatment with berberine downregulates the expression of ABC transporters, including ABCB1 and ABCC1 (also known as multidrug resistance protein 1 (MRP1)), thereby improving anti-growth effects of doxorubicin on breast cancer in vivo." (PMID 34575983, 2021). "In addition, miRNA-298 effectively targeted ABCC1, enhancing the sensitivity to DOX, whereas miRNA-328 and miRNA-487a amplified breast cancer cells’ sensitivity to mitoxantrone (MX) by directly targeting ABCG2." (PMID 34771496, 2021). "ABCC1 and ABCC4 have previously been implicated as negative prognostic indicators for breast cancer." (PMID 33081264, 2020). "By DNA methylation analysis of the ABCB1, ABCC1, and ABCG2 promoters in three breast cancer cell lines (MCF7, luminal A subtype; ZR-75-1, luminal B subtype; MDA-MB-231, triple negative subtype), the ABCC1 promoter has been found to be unmethylated in each of the cell lines." (PMID 33066132, 2020). "In agreement with our results, breast cancer cells overexpressing ABCC1 showed an increase in proliferation, which could be inhibited by MK571, and overexpression of ABCC1 enhanced tumor growth in mice." (PMID 33081264, 2020). "In this study, the role of ABCC1 and ABCC4 in breast cancer progression was investigated." (PMID 33081264, 2020). "In particular, multidrug-resistant protein-1 (ABCC1/MRP1), breast cancer resistance protein (ABCG2/BCRP) and multidrug-resistant protein-8 (ABCC11/MRP8) were expressed significantly more, and more frequently in TNBC compared to other breast cancer subtypes." (PMID 31443516, 2019). "ATP-binding cassette (ABC) transporters have been identified as transporters of S1P in different cell lines, such as ABC subfamily C member 1 (ABCC1) in mast cells, ABC subfamily A member 1 (ABCA1) in astrocytes, or ABCC1 and ABC subfamily G member 2 (ABCG2) in breast cancer cells." (PMID 28890699, 2017). "In conclusion, in-house developed bisulfite PSQ methods were applied to determine the promoter methylation status of ABCB1, ABCC1 and ABCG2 in 19 human cancer cell lines, MDR cell models as well as tumor, tumor-adjacent and tumor-distant tissues from 16 breast cancer patients." (PMID 27689338, 2016). "In addition, we investigated if aberrant promoter methylation levels of ABCB1, ABCC1 and ABCG2 occur in tumor and tumor-surrounding tissues from breast cancer patients." (PMID 27689338, 2016). "Hence, to begin to understand the role of these transporters in breast cancer progression, we first investigated the expression of ABCC3 in grade III invasive breast ductal carcinoma tissue samples and compared it with that of ABCC1 in the same samples." (PMID 27171227, 2016). "Thus, our data revealed that similar to knockdown of ABCC1, ABCC3 knockdown also increased the drug-sensitivity of breast cancer cells." (PMID 27171227, 2016). "A few papers indicate that hypermethylation of the ABCB1 promoter is a frequent event in breast cancer, so far, data on promoter methylation of ABCC1 and ABCG2 has, however, not been published." (PMID 27689338, 2016).